MIR23B (microRNA 23b)
Synonyms: hsa-mir-23b; MIRN23B; miRNA23B; mir-23b
Gene: MicroRNA gene on chromosome 9 (95,085,208 to 95,085,304, forward strand). Ensembl gene ENSG00000207563.
Pathways (Reactome):
Gene expression (Transcription): MicroRNA (miRNA) biogenesis
Signal Transduction: TGFBR3 expression
Gene Ontology:
Biological process: miRNA-mediated post-transcriptional gene silencing
Cellular component: RISC complex
Homologues: Orthologues: chimpanzee ptr-mir-23b (100% identical), macaque MIR23B (88% identical), rabbit MIR23B (84% identical), pig ssc-mir-23b (79% identical), tropical clawed frog xtr-mir-23b (78% identical), guinea pig MIR23B (75% identical), mouse Mir23b (74% identical), dog MIR23B (73% identical), zebrafish MIR23B (70% identical), zebrafish dre-mir-23b (67% identical). Paralogues in human: MIR23A (51% identical).
Diseases named in the same sentence as MIR23B in open-access papers:
MIR23B is named in the same sentence as 5 diseases in open-access papers, as found by Europe PMC text mining. Sharing a sentence is not in itself a finding about the gene and the disease. The quoted sentences say what the papers report.
kidney cancer (1 paper, 2009). Primary or metastatic malignant neoplasm involving the kidney. "In particular, CUL3, over expressed in kidney and prostate cancers, is a target of several dysregulated MIRs: MIR22, MIR23A, MIR23B, MIR218-1, MIR218-2, and MIR301, which are down regulated in kidney cancers, and of MIR22, MIR23A, MIR181A, and MIR181C, which are down regulated in prostate cancers." (PMID 19402918, 2009).
ovarian carcinoma (1 paper, 2016). A malignant neoplasm originating from the surface ovarian epithelium. "Our results show that MIR23B mRNA expression was significantly lower in ovarian carcinomas and borderline tumors than in normal ovarian tissues and benign tumors, and the expression among age and pathological subtypes (mucinous vs. other types) was significantly different." (PMID 26872615, 2016). "MIR23B mRNA expression was significantly lower in the ovarian carcinomas and borderline tumors than in the normal ovarian tissues and benign tumors (p < 0.05), and there were significant differences in expression among ages (p < 0.05) and pathological subtypes (mucinous vs. other types, p < 0.05)." (PMID 26872615, 2016). "We quantified MIR23B and CCNG1 mRNA expression in normal ovary tissue, benign and borderline tumors, and primary ovarian carcinoma using real-time PCR." (PMID 26872615, 2016).
benign tumors (1 paper, 2016). "MIR23B mRNA expression was significantly lower in epithelial ovarian carcinoma and borderline tumors than in normal ovarian tissues and benign tumors, and miR-23b expression among ages and pathological subtypes was significantly different." (PMID 26872615, 2016).
MIR23B also shares sentences with these, for which no sentence is quoted: cancer (1 paper); prostate carcinoma (1).